ERG (ETS transcription factor ERG)
Diseases named in the same sentence as ERG in open-access papers (continued):
Sharing a sentence is not in itself a finding about the gene and the disease.
leukemia (59 papers, 2009 to 2025). A malignant (clonal) hematologic disorder, involving hematopoietic stem cells and characterized by the presence of primitive or atypical myeloid or lymphoid cells in the bone marrow and the blood. "So, it has been proposed that ERG-driven drug resistance overrides PI3K/AKT signaling by alternative pathways which need to be further investigated for effective drug design and adapted therapies for ERG-overexpressing high-risk leukemias." (PMID 39940843, 2025). "Re-expression of IKAROS in B-ALL perturbs ERG-associated transcriptional programs, linking its developmental role to tumor suppressor activity in leukemia." (PMID 41509392, 2025). "It is likely that additional cooperating lesions that can overcome the proliferative deficits associated with RUNX1::ERG are required to induce full-blown leukemia." (PMID 37002311, 2023). "Collectively, the selective separation of LSD1 from GFI1B by NCD38 restores the ERG super-enhancer activation and consequently upregulates ERG expression, inducing the transdifferentiation linked to the anti-leukemia effect." (PMID 29765516, 2018). "ETS transcription factor ERG has been implicated in numerous cancers, including leukemia." (PMID 37735473, 2023). "We found that genome editing of ERG resulted in the loss of leukemia cell growth accompanied by elevated apoptosis in the case of SKNO1 (AML harboring the RUNX1-RUNX1T1 translocation) and TF1 (erythroleukemia) cells, while THP1 cells were not affected by the ERG inactivation." (PMID 37735473, 2023). "Both FLI1 and ERG have also been implicated in normal hematopoiesis and leukemia formation." (PMID 35624144, 2022). "Furthermore, the mutation of SUMO sites in ERG inhibited its ability to promote the proliferation and inhibit the differentiation of leukemia cells." (PMID 33842551, 2021). "We hypothesize that ERG overexpression is associated with primary drug resistance thereby influencing the outcome in leukemia." (PMID 24504051, 2014). "Furthermore, ERG is associated with oncogenic protein complexes in human leukemia." (PMID 37735473, 2023). "Interestingly, leukemia-associated pathways that were regulated by ERG in murine fetal liver-derived HSPCs (Hoxa9-Meis1, CBFA2T3, and repression of myeloid differentiation genes) were ranked at the leading edge of gene sets that were significantly perturbed after HDAC3 inhibition." (PMID 37735473, 2023). "Together, these observations indicate that ERG is a direct IKAROS target and that its repression in B-ALL reflects restoration of a developmental silencing program normally lost in IKZF1-mutated leukemias." (PMID 41509392, 2025). "Another useful marker in pediatric leukemia is the Ets-related gene ERG (erythroblastosis virus E26-transforming sequence family member) which has an important role in early hematopoiesis and hematopoietic stem cell (HSC) maintenance." (PMID 39940843, 2025). "ERG is a versatile oncogene that has been shown to induce the development of various types of leukemia with additional genetic alterations." (PMID 39277669, 2024). "Our study reveals the critical role of a conserved amino acid, proline, at position 199, located at the 3’ end of the PNT (pointed) domain, in ERG’s ability to induce leukemia." (PMID 37735473, 2023). "P199 is necessary for ERG to promote self-renewal, prevent myeloid differentiation in hematopoietic progenitor cells, and initiate leukemia in mouse models." (PMID 37735473, 2023). "Highlighting this interaction as a potential therapeutic target, HDAC3 inhibition led to reduced growth of ERG-dependent leukemia cells in vitro and in vivo." (PMID 37735473, 2023). "The ERG (ETS-related gene) transcription factor is linked to various types of cancer, including leukemia." (PMID 37735473, 2023). "Deregulation of ETS transcription factor gene ERG occurs in 5–10% of DUX4-rearranged leukemia cases." (PMID 35269896, 2022).
leukemia (continued). "ERG promoted expansion and recapitulated molecular signatures of leukemias with high ERG in cord blood progenitors." (PMID 33842551, 2021). "A previous study showed that ERG is capable of promoting the development of leukemia and is crucial for its maintenance." (PMID 33842551, 2021). "We further analyzed the RNA-seq data downloaded from the TCGA leukemia dataset, and the results showed that the ERG expression was significantly upregulated in AML patients compared with normal tissues." (PMID 33842551, 2021). "To elucidate the specific biological functions of ERG in leukemia cells, we stably overexpressed of ERG in K562 and THP1 cells using a lentiviral-based approach." (PMID 33842551, 2021). "In the present study, we stably knocked down or overexpressed ERG in leukemia cells and observed that ERG significantly promotes the proliferation and inhibits the differentiation of AML (acute myeloid leukemia) cells." (PMID 33842551, 2021). "ERG has previously been reported to be involved in myeloid and lymphoid malignancies and plays a crucial role in the progression of leukemia." (PMID 33842551, 2021). "This is consistent with the previous study which showed that ERG promotes the stem cell signature of leukemia cells." (PMID 33584313, 2020). "The results showed that overexpression of ERG significantly increases the 3-fold percentage of total CD117-positive leukemia cells." (PMID 33584313, 2020). "To further study how ERG promotes the generation of CD117-positive leukemia cells, we analyzed the promoter region of CD117, and found several ERG binding sites (CGGA (A/T)." (PMID 33584313, 2020). "In contrast, knockdown of ERG in MA-KO cells decreases 30 percent of the total CD117-positive leukemia cells." (PMID 33584313, 2020). "Previous studies showed the anti-leukemia role of miR-196a as ERG regulators contributed to AML biology." (PMID 32209730, 2020). "The previous study showed that ERG reprograms leukemia cells into CD117-positive leukemia stem-like cells." (PMID 33584313, 2020). "Functional analyses conducted in mice and human CD34 normal and leukemic cells have demonstrated the role of ERG in the induction of early myeloid progenitors in leukemia stem cell through the activation of RAS pathway and Pim1." (PMID 30303964, 2018). "For example, low expression of the brain and acute leukemia cytoplasmic (BAALC) and ETS-related gene (ERG) genes have been associated with better outcome in CN-AML patients." (PMID 29540187, 2018). "In leukemia, ERG targets transcription factors such as GATA2, which is an important regulator of hematopoietic stem cell and megakaryocyte development and, RUNX1, which is involved in the development of normal hematopoiesis." (PMID 30303964, 2018). "Consistently, a signature of ERG-activated genes from literature was significantly enriched in non-ERG-related patients when compared to ERG-related group suggesting an impaired ERG signaling in the ERG-related leukemia subtype." (PMID 28415578, 2017). "All together our data contribute to the knowledge on the recently defined ERG-related leukemia subtype, that despite the presence of IKZF1 deletions are marked by an excellent prognosis." (PMID 28415578, 2017). "The increased expression of ERG promotes hematopoietic stem cell maintenance, is linked to a poor outcome of AML, is associated with chemoresistance in leukemia, and thus is likely to have an adverse effect on AML therapy." (PMID 28301528, 2017). "Recent studies uncovered IGH-DUX4 rearrangements, and rare ERG-DUX4 rearrangements, as universal feature and founder event in the ERG-related leukemia subtype." (PMID 28415578, 2017). "ERG-related leukemia is a BCP ALL subtype firstly identified by Yeoh and colleagues in the beginning of the gene expression era as a group of B-others characterized by a unique gene expression profile." (PMID 28415578, 2017).
leukemia (continued). "In conclusion, our data suggest that neither the expression of aberrant proteins from internally deleted allele nor the reduced expression of wild type ERG seem to provide a plausible explanation of the specific biology of ERG -related leukemia subgroup." (PMID 27494621, 2016). "Further researches still needed to clarify the role of BAALC and ERG in the pathogenesis of leukemia and their importance as targets for treatment of AML." (PMID 27335598, 2016). "Herein we show that in leukemia cells ERG overexpression promotes a mesenchymal-like gene expression signature that includes: CD24, CD44, ITGA10, ITGB5, ITGB3, ITGA2B and the morphogenic-associated genes, such as SHANK3, TYROBP." (PMID 24504051, 2014). "We previously reported that prolonged ERG overexpression induced leukemia cells to adhere and develop bi-directional protrusions (spindle shaped cells)." (PMID 24504051, 2014). "Further studies would be required to determine the precise repair processes coordinated by ERG in leukemia." (PMID 24504051, 2014). "Through fluorescent tracking, we have also demonstrated that ERG overexpression in leukemia cells confers proliferative growth advantage at twice the rate of non-induced cells, whilst mediating the development of spindle shape morphology." (PMID 24504051, 2014). "Some hematopoietic cancers overexpress ERG protein and it is known that myeloid, T- and Bcell leukemias depend on ERG for their maintenance." (PMID 23555854, 2013). "Moreover, RUNX1::RUNX1T1 AML cells are addicted to ERG and RUNX1 with a disbalanced expression in favor of RUNX1::RUNX1T1 causing leukemia cell death." (PMID 39857993, 2025). "None of the patients with identified FLT3 mutations presented recurrent rearrangements in B-ALL or alterations in the IKZF1, PAX5, or ERG genes, suggesting that FLT3 mutation may serve as the driving mechanism for leukemia in these cases." (PMID 39711880, 2024). "The immunophenotype was comparable to what we previously reported for TgERG leukemia regardless of ERG variant, namely lineage negative, c-Kitlow, CD150+ AML." (PMID 37735473, 2023). "We hypothesized that P199L might, therefore, affect the interaction of ERG with one or more proteins essential to the progression of leukemia." (PMID 37735473, 2023). "We demonstrated in a transgenic mouse that ERG is a leukemia oncogene." (PMID 37735473, 2023). "Notably, this notion is consistent with previously reported association of ERG, a ETS family transcription factor, with both AML1-ETO and ETO2-GLIS2 in the corresponding leukemia cells." (PMID 36158200, 2022). "Phosphorylation of serine 283 is exclusively detected in leukemic cells compared to hematopoietic and progenitor stem cells and associates with increased ERG binding to the regulatory elements of specific genes contributing to the malignant phenotype of ERG-driven leukemia." (PMID 35267426, 2022). "Since ERG is frequently overexpressed in a variety of leukemias, ERG SUMOylation may be an important regulator in the occurrence and development of this disease." (PMID 33842551, 2021). "As increasing evidence has shown that the SUMOylation of target proteins plays a crucial role in leukemia, we assessed whether ERG is modified by SUMO." (PMID 33842551, 2021). "To investigate the role of ERG in leukemia, we examined the expression level of ERG in multiple leukemia cell lines, including acute promyelocytic leukemia cell HL60, chronic myelogenous leukemia cell K562, acute monocytic leukemia cell THP1, and histiocytic lymphoma leukemia cell U937." (PMID 33842551, 2021). "Taken together, these results show that ERG promotes the proliferation and inhibits the differentiation of leukemia cells, indicating that ERG plays an important role in regulating the proliferation and differentiation of leukemia cells." (PMID 33842551, 2021). "ERG and gene translocation produce fusion gene products that lead to leukemia." (PMID 33842551, 2021).
leukemia (continued). "Besides a unique GEP we show for the first time that ERG-related leukemia share a highly specific noncoding RNA signature." (PMID 28415578, 2017). "We aimed to elucidate whether ERG deletions could drive the specific biology of this ERG-related leukemia subgroup through expression of aberrant or decreased expression of wild type ERG isoforms." (PMID 27494621, 2016). "Further researches still needed to clarify the role of BAALC and ERG in the pathogenesis of leukemia and their importance as targets for treatment of AML that could be promising due to their high incidence of expression in AML." (PMID 27335598, 2016). "The growth promoting effects of ERG suggest that aberrant regulation of ERG could play an important role in the development of leukemia and other cancers." (PMID 26000093, 2015). "Also, in our leukemia model, ERG under-expressed genes included ATM, CHEK1 and ATR, which are key genes in the initiation of homology-dependent DNA repair." (PMID 24504051, 2014). "We highlight, a number of changes in gene transcription in key pathways responsible for drug resistance, and provide novel targets for further validation and development in order to achieve custom tailored treatment strategies for the high ERG subgroup of leukemia." (PMID 24504051, 2014). "However, the role of ERG and its modification in leukemia remains underexplored." (PMID 33842551, 2021). "To further identify whether ERG directly regulates the CD117-positive leukemia stem-like cell pool, we constructed MA-WT-ERG cells which overexpressed ERG in MA-WT cells and MA-KO-shERG cells which downregulated ERG in MA-KO." (PMID 33584313, 2020). "Furthermore, hsa-miR-100 belonging to the miR-125b-1 cluster (chr11, MIR100HG host gene) and hsa-miR-125a-3p belonging to miR-125a cluster (chr19) were among the top ranked differentially expressed miRNAs, highlighting the involvement of the miR-125 family in the ERG-related leukemia phenotype." (PMID 28415578, 2017). "This further supports the hypothesis that wild type ERG is important for this leukemia subtype." (PMID 27494621, 2016). "Hence, aberrant DNA repair may contribute to the multifactorial drug-mediated resistance in high ERG expressers in leukemia." (PMID 24504051, 2014). "Deregulated expression of multiple ETS factors like ERG, FLI1 and SPI1 contribute to the genesis of leukemia and impact the survival outcome in leukemia patients." (PMID 37895265, 2023). "To evaluate a possible anti-leukemic effect of HDAC3 inhibition in vivo we utilized the SKNO1 leukemia model bearing a RUNX1-RUNX1T1 translocation and ELF-153 complex karyotype AML, which are both addicted to ERG expression and dependent on HDAC3 activity." (PMID 37735473, 2023). "Specifically, in the poor prognosis B-ALL type harboring the TCF3-HLF translocation, ERG cooperates with TCF3-HLF to regulate enhancer functions and is essential for leukemia maintenance." (PMID 37735473, 2023). "Some pluripotency genes were also identified, as well as cancer genes, such as TET1, ALK, EP300, ERG, MKL1 and PHF6, already described as being involved in leukemia." (PMID 37174060, 2023). "The activity of ERG modulates RUNX1-RUNX1T1 expression, prevents oncogene overexpression, and maintains leukemia viability." (PMID 37735473, 2023). "To validate the ERG/NCoR-HDAC3 interaction in models of established leukemia, we confirmed the co-immunoprecipitation of the NCoR-HDAC3 complex with endogenous ERG in human AML cells." (PMID 37735473, 2023). "To elucidate the role of ERG SUMOylation in leukemia cells, we generated stable THP1 cells by lentiviral infection with wild-type (ERG-w) or three SUMOylation sites mutant (ERG-m) ERG plasmids." (PMID 33842551, 2021). "PML plays a key role in the development of leukemia, and recruits proteins for SUMO modification, and we observed that PML promotes the SUMOylation of ERG." (PMID 33842551, 2021).
leukemia (continued). "The results showed that the inhibition of FGFR1 and AKT, not ERK1/2, significantly reduced FGFR1 activation-induced ERG expression in 293T cells and leukemia cells, suggesting that FGFR1 upregulates ERG expression by activating PI3K/AKT signaling." (PMID 33584313, 2020). "Recently, we have shown that leukemia maintenance is dependent on a balance between AML1-ETO, RUNX1, and ERG expression, and that disturbed RUNX1 or ERG function results in AML1-ETO overdose and cell death." (PMID 31869378, 2019). "ERG-related leukemia is a B cell precursor acute lymphoblastic leukemia (BCP ALL) subtype characterized by aberrant expression of DUX4 and ERG transcription factors, and highly recurrent ERG intragenic deletions." (PMID 28415578, 2017). "Expression of a long noncoding RNA proximal to the first exon of ERG, termed “Antisense long noncoding RNA associated with ERG (or ALE)”, was described in the majority of ERG-related cases with IGH-DUX4 rearrangements and confined to this leukemia subtype." (PMID 28415578, 2017). "Within the ETS family transcription factors, ERG has been shown to be physically and functionally associated with AML1-ETO and ETO2-GLIS2 in the corresponding leukemia cells; however, ERG is not expressed in U937 cells." (PMID 36158200, 2022). "ERG not only promotes the generation of CD117-positive leukemia cells by transcriptionally upregulating CD117, but is also an important regulator for the weak pathogenesis of CD117-positive leukemia cells by inhibiting the expression of chemokines genes." (PMID 33584313, 2020). "We conclude that while ERG-related leukemias share most clinical features and can be considered a unique group, some biological differences between ERG deleted and ERG not deleted leukemias are noteworthy." (PMID 28415578, 2017). "In leukaemic cells, ERG phosphorylation is mediated by mitogen-activated protein kinase signal-regulated kinase (MAPK) signalling, which promotes progenitor proliferation and is a potential target for modulating ERG-driven transcriptional programs in leukaemia." (PMID 39827226, 2025). "Recent studies in a prostate cell line over-expressing ERG also concur with our results, i.e. they exhibit highly enriched cell adhesion and cell migration GO terms and promote EMT gene expression, thus providing further support for an ERG-driven mesenchymal-like state in leukemia." (PMID 24504051, 2014). "Thus, PKC kinase inhibitors, WNT inhibitors and Ara-C are predicted not to be effective in clearing ERG overexpressing cells in leukemia." (PMID 24504051, 2014). "Within the most prominent γH2AX regions, we identified B cell precursor-specific genes but also non-B cell-specific genes known to become defective in leukemia (e.g., HIST1 and ERG)." (PMID 28199841, 2017). "ERG knockdown attenuated growth in both Down syndrome and non-Down syndrome AMKL (acute megakaryoblastic leukemia) cell lines, and human leukemia cell lines of various lineage." (PMID 33842551, 2021). "Contrary to typical EMT/MET, the EMT markers E- and N-cadherin were not differentially altered by ERG overexpression, suggesting that the EMT/MET gene signature may be different in leukemia than in breast cancer." (PMID 24504051, 2014).